TMIGD1 (transmembrane and immunoglobulin domain containing 1)
Diseases named in the same sentence as TMIGD1 in open-access papers (continued):
Sharing a sentence is not in itself a finding about the gene and the disease.
tumor (8 papers, 2018 to 2023). "Given the relevance of the Pro305 for Scrib membrane recruitment and its tumor-suppressive activity in cells, we tested the ability of TMIGD1 to recruit Pro305-mutated Scrib to cell-cell junctions." (PMID 37430142, 2023). "The underlying mechanism of TMIGD1 function in inhibition of tumor growth is due its ability to modulate induction of cycle inhibitors, p21CIP1 and p27KIP1." (PMID 29515762, 2018). "Together, these findings support the hypothesis that the function of TMIGD1 as tumor suppressor could be linked to its ability to recruit Scrib to the membrane." (PMID 37430142, 2023). "In addition, intracellular signaling pathways that are activated by TMIGD1 were identified, which has provided the first insights into the molecular mechanisms underlying its tumor-suppressive activity." (PMID 37087524, 2023). "A role of TMIGD1 in recruiting Scrib to the lateral membrane is consistent with a predicted function of TMIGD1 as tumor suppressor protein." (PMID 37430142, 2023). "The cell adhesion molecule TMIGD1 is a newly identified tumor suppressor that regulates critical cellular processes such as cell–cell adhesion, cell migration, cell proliferation and cell cycle." (PMID 34503512, 2021). "TMIGD1 inhibits tumor cell proliferation and cell cycle arrest at the G2/M phase through regulating expression of p21CIP1 (cyclin-dependent kinase inhibitor 1), and p27KIP1 (cyclin-dependent kinase inhibitor 1B)." (PMID 34503512, 2021). "Identification of TMIGD1 as an upstream receptor capable of regulating the activity of ERM family proteins offers new insights into the mechanisms of TMIGD1 tumor suppressor signaling and tumorigenesis." (PMID 34503512, 2021). "In this study, we have demonstrated that TMIGD1 acts as a tumor suppressor and its downregulation is regulated by C/EBPβ." (PMID 29515762, 2018). "Based on these observations, we propose that phosphorylation of p38 by TMIGD1 plays a central role in the TMIGD1's anti-proliferative function in RCC tumor cells." (PMID 29515762, 2018). "Altogether, the data demonstrates that re-expression of TMIGD1 in 786-0 cells inhibits tumor growth and invasion." (PMID 29515762, 2018). "Having confirmed the ability of TMIGD1 to inhibit tumor growth in cell culture and in mouse, we sought to investigate the possible role of TMIGD1 in the invasive characteristics of 786-0 cells." (PMID 29515762, 2018). "Taken together, our data demonstrates that restoring expression of TMIGD1 in 786-0 cells stimulates p38 activation, induces p21CIP1 and p27KIP1, and inhibits tumor growth in cell culture and in athymic mouse." (PMID 29515762, 2018). "Expression of both TMIGD1 and C/EBPβ in normal adjacent renal tissue were high, where expressions of both were significantly low in the tumor region." (PMID 29515762, 2018). "Having observed the inhibitory effect of TMIGD1 in 786-0 cells, we examined the effect of TMIGD1 expression in the tumor formation of 786-0 cells in an athymic nude mouse." (PMID 29515762, 2018). "Despite its tissue-specific expression and its apparent function as tumor suppressor, the mechanisms regulating TMIGD1 gene expression are largely unknown." (PMID 37087524, 2023). "In addition, overexpression of TMIGD1 reduces metastastatic spreading of adoptively transferred tumor cell lines in mice." (PMID 37087524, 2023). "How does TMIGD1 stimulate anti-proliferative responses in RCC tumor cells?" (PMID 29515762, 2018). "Next, we examined C/EBPβ and TMIGD1 expressions in the human RCC tumor tissues." (PMID 29515762, 2018). "The present study identifies TMIGD1 as a novel candidate tumor suppressor gene and provides important insight into pathobiology of RCC that could lead to a better diagnosis and possible novel therapy for RCC." (PMID 29515762, 2018). "Based on these observations we propose TMIGD1 as a candidate tumor suppressor gene." (PMID 29515762, 2018). "TMIGD1 is downregulated in human RCC tumors and RCC tumor cell lines." (PMID 29515762, 2018).
tumor (continued). "Altogether, the data demonstrates that TMIGD1 in the RCC cell lines and in primary RCC tumors is significantly downregulated, suggesting that the reduced expression of TMIGD1 in RCC could play a role in tumor progression." (PMID 29515762, 2018). "The most notable examples of down-regulated genes were GUCA2B (FC = 187), TMIGD1 (FC = 129) and CA1 (FC = 121), while CST1 and S100A2 (FC = 131/88.7, respectively) were highly expressed in tumours but not in normal tissue." (PMID 30231850, 2018).
infection (2 papers, 2018 to 2023). The state of being infected such as from the introduction of a foreign agent such as serum, vaccine, antigenic substance or organism. "Additionally, IPA identified the top significantly affected molecules and G9P infection had a staggering >200 fold-change increase of ANPEP and TMIGD1, suggestive of an increased granulocyte and cell recovery response." (PMID 37515094, 2023).
TMIGD1 also shares sentences with these, for which no sentence is quoted: kidney disease (2 papers); breast carcinoma (1); clear cell renal cell carcinoma (1); colorectal adenoma (1); hyperplastic polyp (1); inflammatory bowel disease (1); lymph node metastasis (1); rectal carcinoma (1).